SHBG (sex hormone binding globulin)
Diseases named in the same sentence as SHBG in open-access papers (continued):
Sharing a sentence is not in itself a finding about the gene and the disease.
hyperthyroidism (continued). "Thyroid changes, such as hyperthyroidism, THR, and men with a family history of thyroid nodules, are the target group for testing the concentration of SHBG." (PMID 40427034, 2025). "SHBG in THR syndrome is a parameter of special value, thus, it may be used to differentiate THR from hyperthyroidism of other entities." (PMID 40427034, 2025). "In a case report by Rojas, a patient with hyperthyroidism and PG showed elevated SHBG, elevated total testosterone, normal free testosterone, normal human chorionic gonadotropin (hCG), and normal prolactin levels." (PMID 39797240, 2024). "High levels of SHBG in TSH-oma and normal levels in RTH syndrome could reflect the expected action of excess T4 and T3 on hepatic SHBG production in hyperthyroidism and resistance to hormone action in RTH syndrome." (PMID 33776916, 2021). "No known SHBG-increasing conditions, for example, hepatic cirrhosis, hepatitis, hyperthyroidism, use of anticonvulsants or HIV, were present in any of our patients." (PMID 24028544, 2013). "Notably, P6 also had a profile similar to P3; however, in this patient with TSH cosecretion, a slightly elevated total testosterone may be the effect of an increase in sex hormone-binding globulin due to hyperthyroidism rather than LH cosecretion, as LH immunostaining was negative." (PMID 37988667, 2023).
gestational diabetes (24 papers, 2014 to 2025). Carbohydrate intolerance first diagnosed during pregnancy. "Lower circulating levels of SHBG have also been associated with the development of gestational diabetes mellitus causing increased maternal and neonatal morbidity." (PMID 38337532, 2024). "Maternal serum SHBG levels are also closely linked to PNMS as a predictor of gestational diabetes and pre-eclampsia." (PMID 37573326, 2023). "Several studies have highlighted that elevated levels of testosterone and decreased sex hormone-binding globulin (SHBG) are independent risk factors for gestational diabetes mellitus (GDM) in patients with PCOS." (PMID 37268889, 2023). "On the other hand, in a study of 180 pregnant women with PCOS, an increase in SHBG concentration by 1 nmol/L reduced the risk of developing gestational diabetes by 7%." (PMID 35140785, 2022). "A previous study assessed SHBG levels in women with PCOS, and found that low SHBG levels were associated with gestational diabetes mellitus." (PMID 34977197, 2021). "Some other studies found low SHBG levels being the risk factor for gestational diabetes." (PMID 35140785, 2022). "Low circulating SHBG levels are associated with the development of type 2 and gestational diabetes." (PMID 35140785, 2022). "In addition, women with a reduced concentration of SHBG in the first trimester of pregnancy are at increased risk of developing gestational diabetes later in pregnancy." (PMID 28279160, 2017). "Finally, the results of a meta-analysis of 26 studies showed that SHBG testing in early pregnancy may be a marker of the risk of developing gestational diabetes." (PMID 35140785, 2022). "This is somewhat surprising with regard to SHBG since it is well-established that low SHBG level is a good predictor of gestational diabetes." (PMID 39410647, 2024). "Early pregnancy SHBG was inversely associated with fasting glucose levels later in mid-pregnancy; moreover, SHBG has been proposed as a clinical predictor of gestational diabetes mellitus." (PMID 37505555, 2023). "For instance, in a large, nested case–control study, individuals who went on to develop gestational diabetes had higher early pregnancy testosterone and lower SHBG compared to controls." (PMID 37505555, 2023). "A previous study evaluated SHBG levels in women with PCOS and found an association between low SHBG levels and subsequent development of gestational diabetes mellitus." (PMID 33101409, 2020). "SHBG levels were reported to be lower in women with gestational diabetes and in those who require insulin therapy." (PMID 28279160, 2017). "Since SHBG is expressed in the placenta, and the mRNA is reduced in mothers with gestational diabetes, we studied SHBG in neonates on day 2 as well as in cord blood." (PMID 27462374, 2016). "In one study of women from China, cord blood SHBG levels were lower among babies born to overweight mothers, most of whom had gestational diabetes." (PMID 26761949, 2016). "In a previous study, insulin and SHBG levels in cord blood were likewise inversely related among mothers with gestational diabetes." (PMID 27462374, 2016). "Therefore, age, BMI, HOMA-IR, Fins, testosterone, androstenedione, and SHBG are important predictors of gestational diabetes in PCOS patients before pregnancy." (PMID 34397795, 2021). "Furthermore, lower first-trimester SHBG levels were found to predict subsequent gestational diabetes mellitus." (PMID 28279160, 2017). "Some studies also indicate that SHBG can be an important factor involved in IR and glucose transport in gestational diabetes mellitus (GDM)." (PMID 40427034, 2025). "Therefore, SHBG holds potential as a biomarker for gestational diabetes mellitus (GDM)." (PMID 39876919, 2024). "This study was conducted to compare maternal serum SHBG level between pregnant women with normal glucose tolerance and those with gestational diabetes (GDM) and to investigate the roll of SHBG in GDM diagnosis." (PMID 28279160, 2017).
gestational diabetes (continued). "Finally, intrahepatic fat was reported to be higher in infants born to obese mothers with gestational diabetes compared to infants of nondiabetic normal-weight mothers, and hepatic fat is known to be inversely associated with SHBG; however, hepatic fat was not measured in the newborns in this study." (PMID 27462374, 2016). "We did not see a significant difference in the pre-pregnancy androgen or SHBG levels in our PCOS patients who did or did not develop gestational diabetes." (PMID 39410647, 2024). "Pre-pregnancy SHBG level was shown earlier to be a predictor of infant birth weight independent of gestational diabetes and pre-pregnancy BMI." (PMID 39410647, 2024). "Women who develop gestational diabetes have 1.5–2.5 times higher E2:SHBG ratios than those who do not." (PMID 25101056, 2014). "Studies have explored the role of SHBG in type 1 diabetesmellitus (T1DM) and its predictive value in gestational diabetes mellitus (GDM)." (PMID 39411775, 2024). "Therefore, further comprehensive research iswarranted to explore the relationships between serum levels of sex hormone-binding globulin (SHBG), insulin-like growth factor-1 (IGF-1), and cortisol and gestational diabetes mellitus (GDM) in greater depth." (PMID 39876919, 2024).
coronary heart disease (22 papers, 2014 to 2025). "Studies have shown that SHBG regulates the activity of myocardial fibroblasts, thereby reducing the risk of coronary heart disease and its remodeling." (PMID 40427034, 2025). "A Mendellian randomisation study also showed genetically predicted higher SHBG was associated with lower risk of ischemic heart disease in men." (PMID 37730580, 2023). "In the MESA study, lower 25(OH)D levels were found to be associated with lower sex-hormone-binding globulin concentrations and higher levels of free testosterone, which are important in the course of coronary artery disease." (PMID 35160231, 2022). "We consider an example of Mendelian randomization analysis with serum testosterone as the risk factor and coronary artery disease (CAD) risk as the outcome using genetic variants in the SHBG gene region." (PMID 28944551, 2017). "Low levels of SHBG were correlated with cardiac risk since HDL-L levels were lower than the normal threshold in patients with coronary heart disease, and this correlation might be affected by SHBG polymorphism." (PMID 34335746, 2021). "After evaluating the association between SHBG and the risk ofcoronary heart disease (CHD) incidence in the United Kingdom Biobank (UKB), Li andcols." (PMID 40857627, 2025). "A similar protective effect can be observed in the connection between genetically predicted SHBG and ischemic heart disease (IHD) in men." (PMID 38895700, 2024). "We conclude by examining two case studies, assessing the effects of low‐density lipoprotein‐cholesterol and serum testosterone on coronary heart disease risk using variants in the HMGCR and SHBG gene regions, respectively." (PMID 36273411, 2023). "Nevertheless, the evidence of effect of SHBG on coronary atherosclerotic outcomes, especially on coronary artery disease, is conflicting." (PMID 35218343, 2022). "In a study of coronary artery disease, long repeats in the SHBG gene promoter (the (TAAAA)n) were associated with low SHBG and with increased severity of coronary artery disease on angiography." (PMID 30321217, 2018). "Previous MR studies have suggested that calcium increases the risk of ischemic heart disease (IHD) and SHBG reduces it, so these mechanisms together might have a relatively neutral effect on IHD in women." (PMID 34187478, 2021). "Observational studies indicate that serum sex hormone-binding globulin (SHBG) levels are inversely correlated with blood lipid levels and coronary heart disease (CHD) risk." (PMID 38796576, 2024). "Of these 46 differences most were in magnitude but not direction, such as for SHBG, ischemic heart disease, heart attack, and facial aging, while 11 were directionally different." (PMID 40498079, 2025).
Hyperglycemia (22 papers, 2014 to 2024). An increased concentration of glucose in the blood. "Hyperglycemia, which is usually found in obese men, seems to cause a decrease in sex hormone-binding globulin (SHBG) production by the liver." (PMID 33324496, 2020). "A similar pattern was observed for SHBG and FT, with the exception that low FT and SHBG concentrations were also strongly linked to prevalent hyperglycaemia." (PMID 25019163, 2014). "According to this,lower SHBG levels may be regarded as a risk factorfor the development of hyperglycaemia, insulinresistance,and/or DM II in young patients withAGA." (PMID 32681618, 2020). "After adjusting for overweight and covariates, lower SHBG and FSH levels were associated with higher hyperglycemia risk (OR = 0.70 and 0.69, all p < 0.05)." (PMID 36767197, 2023). "Considering single sex hormone mediators, decreasing SHBG and FSH levels of overweight/obese women increases the risk of hyperglycemia incidence by 0.74-fold and 0.81-fold, respectively." (PMID 36767197, 2023). "Women with early‐onset GDM had 6.7% (95% CI 0.7%–12.7%) lower SHBG levels and women who needed insulin for fasting hyperglycaemia 8.7% (95% CI 1.8%–14.8%) lower SHBG levels than other women with GDM." (PMID 36484476, 2023). "The results showed that even though there were subtle differences in the subgroup analyses, both SHBG and FSH mediated the association between overweight and hyperglycemia to varying degrees." (PMID 36767197, 2023). "A pooled score aggregating characters from multiple sex hormones mediated more than one-third of the overweight-hyperglycemia association, with positive correlations with T, E2 and negative correlations with SHBG, FSH, and DHAS." (PMID 36767197, 2023). "In contrast to IR, the risk of hyperglycemia per se was not dependent on androgen or SHBG levels, only BMI had a statistically significant influence with an OR of 1.10 (p < 0.001)." (PMID 33670546, 2021). "Other metabolic disorders concomitant with NAFLD, such as hyperglycaemia might also directly decrease the expression of SHBG." (PMID 30455723, 2018). "In conclusion, lower SHBG levels in early pregnancy were associated with an increased risk for GDM, especially early‐onset disease, higher fasting glucose, and insulin treatment for fasting hyperglycaemia, whereas high T and FAI levels were associated with higher post‐prandial glucose values." (PMID 36484476, 2023). "Hyperglycemia and a high carbohydrate diet which decrease HNF 4-α transcript levels, simultaneously reduce SHBG expression and serum SHBG concentrations." (PMID 32326011, 2020).
non-alcoholic fatty liver disease (22 papers, 2016 to 2026). "Consistent with this, lower endogenous SHBG levels have been robustly associated with increased risk for cardiometabolic disorders and non-alcoholic fatty liver disease across both sexes and age groups." (PMID 41586225, 2025). "This variant mapped to the nearby gene PNPLA3, a well-established locus associated for non-alcoholic fatty liver disease, multiple liver enzymes measures, hemotological traits, sex-hormone binding globulin levels, and T2D." (PMID 35186008, 2021). "A meta-analysis confirmed these observations, showing that low SHBG levels correlate with non-alcoholic fatty liver disease (NAFLD) in both women and men." (PMID 36968815, 2023). "The purpose of this study is to establish a novel nomogram model for accurate detection of non-alcoholic fatty liver disease (NAFLD) in the Chinese population based on sex hormone binding globulin (SHBG) and other routine laboratory tests." (PMID 37334312, 2023). "The association between menopause and non-alcoholic fatty liver disease (NAFLD) may be influenced by individual variations in estrogen, androgen, sex hormone-binding globulin (SHBG), and gonadotropin secretion." (PMID 38891156, 2024). "Furthermore, low SHBG levels have been observed in patients with non-alcoholic fatty liver disease, and it is possible that higher ectopic fat in the liver inhibits liver function and reduces SHBG production." (PMID 39433891, 2024). "Our previous study has found that low serum SHBG, but not androgen, is independently associated with non-alcoholic fatty liver disease (NAFLD) in T2D patients." (PMID 29109457, 2017).
liver disease (21 papers, 2012 to 2025). "Patients with liver disease caused by hemochromatosis typically develop hypogonadotropic hypogonadism from pituitary iron accumulation, often accompanied by mildly elevated SHBG." (PMID 40863113, 2025). "Previous studies have indicated that sex hormones and sex hormone-binding globulin are associated with LF, liver fat, and liver disease." (PMID 38326881, 2024). "SHBG concentration is strongly influenced by various factors, such as sex steroid balance, drugs, thyroid hormone, insulin, dietary composition, and liver diseases." (PMID 30881692, 2019). "SHBG levels are also markedly increased with hepatitis-B or hepatitis-C infection, while patients with liver disease due to hemochromatosis develop hypogonadotropic hypogonadism due to pituitary iron deposition and tend to have slightly elevated SHBG levels." (PMID 26761949, 2016). "Liver diseases influence SHBG levels through multiple pathways." (PMID 40863113, 2025). "Essentially, we found that sex hormone binding globulin (SHBG) below 33.4 nmol/l was able to predict a high risk for NAFLD in women consulting for PCOS, thus suggesting it as a possible biochemical hallmark of this hepatic disease." (PMID 33854482, 2021). "The most surprising results in this work are the high importance of cystatin C, gamma glutamyltransferase, and SHBG in predicting liver disease—as these are not part of the American Association for the Study of Liver Diseases (AASLD) guidelines for diagnosing acute liver disease." (PMID 34209487, 2021). "Finally, we did not have liver biopsies available and were therefore unable to evaluate whether SHBG levels correlate with histologic severity of liver disease in our cohort." (PMID 32128321, 2019). "Finally, individuals were not excluded based on health status, therefore some individuals with chronic conditions that may affect hepatic production of or clearance of proteins including SHBG such as liver disease, renal disease, or severe malnutrition, may have been included in this analysis." (PMID 22829776, 2012). "The connection between serum SHBG concentrations and liver diseases is not new, but was discovered nearly 40 years ago." (PMID 37685811, 2023). "This implies that in conditions with a known increase of SHBG, such as HIV infection, liver disease, old age, TT may be normal or even higher, but free (and, therefore, active) testosterone may be low." (PMID 33289905, 2021).
endometriosis (16 papers, 2020 to 2025). The growth of functional endometrial tissue in anatomic sites outside the uterine body. "The present study was devoted to identifying the link between the GWAS-validated genetic determinants of SHBG and the risk of endometriosis in Caucasian women of Russia." (PMID 41373783, 2025). "SHBG-raising genotype GG rs440837 (A > G) ZBTB10 and GWAS-substantial intergenic interactions affect the level of seven SHBG SNPs and increase the risk of endometriosis in Caucasian women of Russia." (PMID 41373783, 2025). "The study was devoted to identifying the link between the genetic determinants (single nucleotide polymorphisms [SNPs]) of SHBG (according to predating genome-wide associative studies [GWAS]) and the risk of endometriosis in the Caucasian women of Russia." (PMID 41373783, 2025). "An increase in the SHBG concentration, in turn, will determine a significant decrease in free testosterone in a woman, and this will eventually increase the risk of endometriosis, which we found in our study." (PMID 41373783, 2025). "Well, we found that SHBG-raising genotype GG rs440837 (A > G) ZBTB10 causes an almost twofold increase in the endometriosis risk (OR = 1.91)." (PMID 41373783, 2025). "At the same time, endometriosis is characterized by a clear association between high SHBG and an increased risk of disease." (PMID 40724651, 2025). "In contrast to PCOS, endometriosis is associated with increased SHBG and reduced serum and follicular testosterone." (PMID 34295358, 2021). "Regular exercise may lower estrogen levels, improve insulin sensitivity, and raise SHBG, contributing to a reduced risk of endometriosis through anti-inflammatory mechanisms." (PMID 40507748, 2025). "According to the results of previous studies, caffeine, alcohol, and smoking can cause changes in the synthesis of known sex steroids (SHBG), which may affect the risk of hormone-related diseases, such as endometriosis." (PMID 38378552, 2024). "The authors point out that intercellular SHBG, which is excessively formed in endometrioid tissue, “protects” related estrogens from metabolic inactivation in the liver and makes them more accessible to endometrial cells, thereby causing an increased risk of endometriosis." (PMID 41373783, 2025). "Emerging evidence indicates that dietary patterns may modulate the inflammatory environment associated with endometriosis, potentially influencing symptom severity by affecting oxidative stress, estrogen metabolism, and levels of sex hormone-binding globulin (SHBG)." (PMID 40507748, 2025). "Nine polymorphisms studied in our work have a significant effect on the content of SHBG in the female organism (they account for 8.4% of the variability in the SHBG level), seven of which (according to our results) determine the predisposition to endometriosis in Caucasian women of Russia." (PMID 41373783, 2025). "The literature materials about the link of SHBG level/expression with endometriosis are very contradictory." (PMID 41373783, 2025). "A decrease in the SHBG level (and an increase in free testosterone content) in endometriosis patients during treatment with danazol has been shown in other studies." (PMID 41373783, 2025). "Genetic correlation analysis revealed apolipoprotein A, HDL cholesterol, triglycerides, testosterone, SHBG and alanine aminotransferase were all significantly correlated with endometriosis and passed the stringent Bonferroni-corrected P value threshold." (PMID 38049874, 2023). "In a multivariable model including SHBG, the effect of overall testosterone on endometriosis was retained (b = − 0.21, P = 5.03 × 10−5)." (PMID 38049874, 2023). "As the majority of testosterone is bound to SHBG and inactive, we also considered the effect of bioavailable testosterone on endometriosis." (PMID 38049874, 2023).